AQP3 (aquaporin 3 (Gill blood group))
Diseases named in the same sentence as AQP3 in open-access papers (continued):
Sharing a sentence is not in itself a finding about the gene and the disease.
cancer (continued). "AQP3, as a therapeutic target for inhibiting high AQP3 expression in NSCLC tissues, may weaken cancer cell proliferation, invasion, and metastasis." (PMID 22814259, 2012). "We showed that although silencing of AQP3 protein did not affect cell proliferation (data not shown), it resulted in increased sensitivity of cancer cell to cryoinjury compared with untreated cells." (PMID 19513079, 2009). "Moreover, the prolonged oxidative stress caused changes in AQP3 and AQP5 expression only in the cancer cell lines, in contrast to their non-malignant counterparts." (PMID 38929065, 2024). "Thus, the homogenous expression of AQP3, AQP7 and AQP9 may aid the cancer cells in their adaptations to high osmotic stress as well as facilitate H2O2-mediated signaling—both of which may aid cancer cell survival." (PMID 37681917, 2023). "The homogenous expression of AQP3, AQP7 and AQP9 suggests that the cancer cells have a high capacity for glycerol uptake, which may contribute to the increased energy consumption of the cancer cells." (PMID 37681917, 2023). "Furthermore, AQP3-mediated H2O2 transport has been correlated to breast cancer cell migration, and AQP5 facilitating transmembrane H2O2 diffusion is able to modulate cell proliferation of cancer yeast cells in response to oxidative stress." (PMID 36077720, 2022). "In order to define AQP3 and AQP5 as targets for cancer treatment, it is needed to thoroughly study all possible aspects and pathways affected, as inadequate inhibition or stimulation of each AQP could drive cancer cells to the more malignant phenotype." (PMID 33947079, 2021). "However, mechanisms by which AQP3 influences human reproduction are not as clear as those by which malignant tumor metastasis is promoted." (PMID 33781292, 2021). "Further work is needed to investigate whether mechanisms of AQP3- and AQP8-facilitated cancer cell migration and invasion involve cell volume regulation, protrusion formation, cytoskeletal interaction, or other functional properties of the AQP channels that remain to be defined." (PMID 29922644, 2018). "These dual correlations imply that, according to specific stimuli, AQP3 could play a role in epithelial–mesenchymal transition (EMT), facilitating dynamic shifts between epithelial adhesion and mesenchymal motility, which are crucial processes in development, wound healing, and cancer progression." (PMID 40305202, 2025). "We analyzed the expression of AQP3, PI3K, and pAkt/Akt as a part of EGFR/PI3K/Akt pathway, as well as NRF2 in three cancer cell lines and nontumorigenic cell line in order to investigate the influence of lipid raft disruption and EGF treatment on these proteins." (PMID 37175840, 2023). "A high expression of AQP3 was significant in cancer tissue when compared to the control group (p < 0.001), whereas a low AQP4 membrane expression was noted as significantly common in cancer tissue compared to non-neoplastic lung tissue (p < 0.001)." (PMID 36233821, 2022). "ACC had low or no AQP3 and AQP5 expression when compared to normal tissues, which might be due to a downregulation of these proteins during de-differentiation and cancer development." (PMID 32630469, 2020). "The real-time PCR results for AQP3 and RPL37 did not concur with L-SAGE data and may be due to interindividual differences rather than a representation of changes present in CIN lesions or cancer." (PMID 17543121, 2007).
tumor (99 papers, 2012 to 2026). "After oral glycerol administration, ATP levels and epidermal cell proliferation were reestablished, suggesting that AQP3-facilitated glycerol permeability contributes to the generation of ATP and is implicated in tumor growth." (PMID 39941100, 2025). "AQP3, 4 and 5 are expressed in H1299 cell line, derived from the lymph nodes and has been widely used to investigate various disease-associated tumor metastases." (PMID 39611488, 2025). "Higher levels of JUN, MXD1, AQP3 were associated with a better OS, and all three of them were upregulated by deslanoside, suggesting their tumor suppressor role in PCa." (PMID 34830961, 2021). "In this case, decreased AQP3 expression is associated with a more aggressive tumor behavior, suggesting that AQP3 is related to cellular differentiation, but not proliferation." (PMID 32075009, 2020). "Upregulated of AQP3 was associated with tumor differentiation (p = 0.028), TNM stage (p = 0.029), and BCLC stage (p = 0.02)." (PMID 29415990, 2018). "The pro-tumourigenic effect of a loss of AQP3 has been investigated in previous studies on other tumour entities." (PMID 23043286, 2012). "We created two types of AQP3-associated tumor models to explore the role of AQP3 on LUAD in vivo." (PMID 39060229, 2024). "The increased expression of AQP3 in tumor stem cells may lead to the downregulation of genes linked to the Wnt/GSK-3β/β-catenin pathway, specifically GSK-3β and β-catenin." (PMID 39440058, 2024). "Impaired phorbol ester 12-O-tetradecanoylphorbol 13-acetate (TPA)-mediated proliferation was seen in the AQP3-deficient epidermis during the tumor promotion step, and the author postulated that this is due to the lack of promotion of the initiated cells, resulting in the absence of papillomas." (PMID 35847914, 2022). "Overexpression of AQP3 was observed in ER-positive breast cancer tissues obtained from premenopausal patients when compared to those obtained from postmenopausal patients and is associated with the tumor histological grade and lymph node metastasis." (PMID 31379986, 2019). "It was of note that 40% of stage pT1 UBC tumours exhibited loss of AQP3 protein expression." (PMID 23043286, 2012). "In comparison to non-transduced CD7N cells and Bulk CAR-T cells, scRNA-seq analysis of CD7N CAR-T cells revealed a unique AQP3+ CD4+ T-cell subset following exposure to tumor cells." (PMID 41742839, 2026). "HCV suppresses miR 124 expression, whereas forced expression reduces AQP3 levels and inhibits tumor progression." (PMID 41465470, 2025). "AQP3 knockdown inhibits tumor angiogenesis by reducing CD31 immunostaining, HIF-2α expression, and VEGF expression." (PMID 39440058, 2024). "In human CRC cells, overexpression of AQP3 can promotes cell migration, indicating tumor metastasis and poor prognosis in CRC." (PMID 39346734, 2024). "Among all cytokines, only IL-6 mRNA expression was significantly downregulated in tumor cells co-cultured with AQP3-inhibited M2 macrophages." (PMID 39060229, 2024). "A greater tumour phase was related with lower levels of AQP3 expression in an investigation of 94 patients with bladder cancer." (PMID 38336645, 2024). "In summary, the reduction of NOX4-derived H2O2 by DPI or NAC, or the attenuation of AQP3 as the ROS transport channel, led to a decrease in tumor cell metastasis to the lungs." (PMID 38230207, 2024). "And then, AQP3’s effects on the TME of LUAD were examined using scRNA-seq on fresh tumor samples and adjacent tissues from five treatment-naïve stage I LUAD patients." (PMID 39060229, 2024). "The PPAR-γ/NF-κB axis is the upstream signal pathway of AQP3-mediated M2 macrophage polarization, while IL-6 is the key downstream molecule of AQP3-mediated tumor progression." (PMID 39060229, 2024). "The results suggest a positive correlation between the overexpression of AQP1 and AQP3 and the heightened proliferation and migration capabilities of tumor cells." (PMID 39440058, 2024).
tumor (continued). "The findings from both in vivo and in vitro suggest that AQP3 regulates the M2 macrophage polarization in the tumor microenvironment and affects LUAD development." (PMID 39060229, 2024). "Future studies using a conditional knockout mice model will be essential to finally demonstrate the role of AQP3 in tumor progression." (PMID 39060229, 2024). "Co-culture experiments were performed to further explore the possible effect exerted by AQP3 on the tumor in vitro." (PMID 39060229, 2024). "The elevated expression of AQP1 and AQP3 not only stimulates tumor angiogenesis but also facilitates tumor proliferation and migration." (PMID 39440058, 2024). "The results suggest that AQP3 plays a key role in tumor development by mediating M2 polarization and IL-6 secretion." (PMID 39060229, 2024). "To dissect the mechanism of how AQP3 affects tumor cell proliferation, we performed RNA-seq with control or AQP3 knockdown HepG2 cells after LPS stimulation." (PMID 38463942, 2024). "In summary, the present study demonstrates AQP3 regulates tumor cell proliferation and migration by interfering with M2 macrophage polarization." (PMID 39060229, 2024). "Our results demonstrated that AQP3 relied on the PPAR-γ/NF-κB axis to regulate tumor occurrence and progression by mediating M2 macrophage polarization and IL-6 secretion." (PMID 39060229, 2024). "AQP3 expression also positively correlate with tumor progression, but in advance-stage prostate tumors with high Gleason score (GS, 9–10), a decrease was observed in its expression." (PMID 36672280, 2023). "In conclusion, our data suggested that the expression levels of AQP1, AQP3 and AQP5 were associated with regional lymph node metastasis, histological grading, and tumor location of CRC, respectively." (PMID 37334171, 2023). "The current study reveals for the first time the ability of RoT to inhibit AQP3 activity, an aquaporin with a key role in tumor growth and spread by mechanisms still under investigation." (PMID 36983077, 2023). "While AQP1 was downregulated in the tumor samples, AQP3 was particularly overexpressed in low-grade invasive tumors." (PMID 37761834, 2023). "AQP subtypes, such as AQP1, AQP3, and AQP5, have been implicated in various aspects of carcinogenesis, tumor progression, and invasion." (PMID 38057925, 2023). "Researchers have also demonstrated that co-expression of AQP3 and AQP5 is associated with aggressive tumor progression as well as poor outcomes in esophageal squamous cell carcinoma." (PMID 36672280, 2023). "In a subsequent study, the Aqp3−/− mice showed reduced tumour formation when submitted to topical application of a carcinogen followed by treatment with a tumour promoter." (PMID 35409378, 2022). "In GC, overexpression of AQP3 and its tumor-promotive roles were also confirmed both in vitro and in vivo." (PMID 35957833, 2022). "Overall, our findings firstly indicated that LINC00659 served as a tumor promoter in GC by acting as a molecular sponge of miR-370 to modulate AQP3 expression." (PMID 35957833, 2022). "Autophagy is necessary to maintain the stemness of CSCs in various tumor types, and another aquaporin family member, AQP3, which has been shown to facilitate chemoresistance by stimulating autophagy." (PMID 36372898, 2022). "The current study demonstrates that AQP3 contributes to tumor cell clustering through cell surface membrane protrusion." (PMID 33924231, 2021). "Combined levels of AQP3 and AQP5 protein in biopsy samples from TNBC patients were positively associated with tumor size, lymph node metastasis, and likelihood of relapse, indicating increased aquaporin expression was linked to poorer survival." (PMID 33499000, 2021). "To verify the role of AQP3 as a tumor promoter, we interfered with the expression of AQP3 in BGC823 and SGC7901 cells." (PMID 33993193, 2021).
tumor (continued). "Decreased expression of AQP3 in PC cells increased tumor sensitivity to cryotherapy, a method used to selectively destroy PC tumors while preserving vital structures such as bladder and bowel." (PMID 33499000, 2021). "AQP3 was found to be significantly related to the clinical tumor stage, and lower AQP3 expression indicated a better prognosis in stage I LUAD patients." (PMID 34708074, 2021). "It is becoming increasingly evident that AQP3 is expressed in multiple malignant tumor cells and participates in both tissue oncogenicity and tumor cell migration." (PMID 33781292, 2021). "Existing data concerning other forms of AQPS indicated that auphen (AQP3 inhibitor) decreased expression of AQP3 aquaporins and suppressed the development and tumor growth of xenografts of the HCC cell line." (PMID 32850012, 2020). "Upregulation of Kv11.1 expression was associated with advanced tumor grade and high expression of Ki67 proliferative marker, whereas TRPV6, TRPM8 and AQP1/AQP3 channels were positively correlated with tumor stages III and IV and large tumor size." (PMID 33178018, 2020). "circHIPK3 knockdown suppressed Huh7 xenograft tumor growth and results indicated that circHIPK3 sponged miR-124 to regulate AQP3 expression in HCC." (PMID 32500032, 2020). "It was also noticed that the expression of AQP1 and AQP3 was increased in the advanced stage of cancer, the larger tumor, in patients with metastases, which correlates with the patient’s prognosis." (PMID 33271827, 2020). "After 21 days post cell injection, lower tumor weight and volume were observed in Lv-AQP3-shRNAs HCCLM3 and HUH7 groups as compared with the Lv-AQP3-NC groups." (PMID 31197130, 2019). "According to IHC in 120 HCC patients, AQP3 protein was found to be primarily expressed in the cytomembrane of the tumor cells." (PMID 31197130, 2019). "AQP3 activity is further necessary for the expression of other downstream signaling proteins that play critical roles in tumor development and progression." (PMID 30555637, 2018). "AQP3 was dramatically upregulated in HCC tissues, and high expression of AQP3 was correlated with tumor progression, metastasis, and prognosis in HCC patients." (PMID 30072625, 2018). "In vivo study also confirmed that circHIPK3 depletion suppressed HCC tumor growth via the miR-124 target AQP3." (PMID 29415990, 2018). "A strong immunoreactivity for AQP3 and AQP5 is observed in the ductal cells of patients with pancreatic ductal adenocarcinomas that is associated to tumor aggressiveness and tumor differentiation, respectively." (PMID 29675407, 2018). "AQP3 plays a significant role in tumor biology as it alters cellular signaling; downstream protein expression patterns, encourages tumor development, and mediates cell migration." (PMID 30555637, 2018). "Compared with the null control group, the tumor volume and weight were lower in the group that received AQP3 knockdown MGC803 cells (P < 0.05), whereas that in the group that received AQP3-overexpressing AGS cells was higher (P < 0.05)." (PMID 26918728, 2016). "Abnormal AQP3 overexpression in tumor cells of different origins has been reported and a role for this enhanced AQP3 expression in cell proliferation and tumor processess has been indicated." (PMID 26367709, 2015). "A widely accepted idea to explain the role of AQP3 in tumor cell proliferation allude to the fact that expression of this protein confers to the cell with a higher glycerol permeability and ATP content, which are required for a greater biosynthesis demand." (PMID 26367709, 2015). "AQP3-facilitated glycerol transport was found to determine cellular ATP levels and therefore be important for hyperproliferation and tumor cell proliferation in epidermal mice cells." (PMID 24653705, 2014). "AQP3 has been established as a critical determinant of tumor growth and spread of human GC in previous studies." (PMID 24887009, 2014).
tumor (continued). "We observed the coexpression of AQP3 and AQP5 to be associated with tumor stage, tumor grade, tumor metastasis, and patient prognosis." (PMID 24224160, 2013). "In this study, we also found that the overexpression of both AQP3 and AQP5 was associated with advanced tumor stage, positive distant metastasis, and unfavorable prognosis." (PMID 24224160, 2013). "We further revealed that AQP3 was a transcriptional target of Notch signaling, a critical pathway regulating keratinocyte differentiation and tumor suppression, and it regulated differentiation through a reciprocal negative feedback loop with Notch1." (PMID 24260356, 2013). "In a preliminary analysis of AQP3 expression in tumour specimens of various stages of UBC, we demonstrated loss of AQP3 protein expression in muscle-invasive disease whereas pTa specimens were shown to invariably express the marker." (PMID 23043286, 2012). "Future work analyzing an appropriate number of AQP3-positive tumours is required to address this important aspect." (PMID 23043286, 2012). "1-, 2- and 4-year progression-free survival (PFS) was 97%, 86% and 20% in patients with AQP 3-negative tumours and statistically significantly worse compared to 98%, 98% and 72% in patients exhibiting AQP3+ tumours (p=0.02)." (PMID 23043286, 2012). "Therefore, the role of AQP1, AQP3 and AQP5 in tumor development is closely associated with their peroxiporin function." (PMID 39941100, 2025). "CCK-8, EdU, and transwell assays showed that IL-6 could reverse the inhibitory effects of proliferation and migration of tumor cells owing to AQP3 knockdown in co-cultured model." (PMID 39060229, 2024). "Mixed subcutaneous transplanted tumor mice and Aqp3 knockout mice models were further utilized, and revealed that AQP3 played a critical role in mediating M2 macrophage polarization, modulating glucose metabolism in tumors, and regulating both upstream and downstream pathways." (PMID 39060229, 2024). "AQP3 may affect tumor progression by reducing differentiation and inhibiting apoptosis of LC stem cells through the Wnt/GSK-3β/β-catenin pathway." (PMID 39346734, 2024). "This, in turn, promotes the expression of AQP3 and the proliferation and migration of tumour cells." (PMID 39440058, 2024). "In contrast, AQP3 overexpression in M2 macrophages could promote tumor cells proliferation and migration." (PMID 39060229, 2024). "AQP3/STAT3/CD133 signaling plays a major role during tumor progression in HCC." (PMID 35820920, 2022). "The before-mentioned findings are comparable to previous research in which AQP3 has been suggested to have a significant role in tumor biology as it alters cellular signaling, encourages tumor development, and contributes to proliferation, epithelial–mesenchymal transition and metastasis." (PMID 36233821, 2022). "Moreover, after tumour promoter activation, the Aqp3 knockout mice showed less epidermal thickening and a smaller increase in the number of proliferating cells compared with the wild-type mice." (PMID 35409378, 2022). "In fact, qPCR analyses validated that AQP3 was dramatically up-regulated in GC tumor samples." (PMID 35957833, 2022). "In vivo, Auphen could regulate the expression of AQP3 to inhibit tumor growth and promote apoptosis." (PMID 35972604, 2022). "Of interest, AQP3 was significantly correlated with the clinical tumor stage and lower AQP3 expression showed favorable prognosis in stage I LUAD patients, which indicated that AQP3 may be a potential prognostic biomarker for patients." (PMID 34708074, 2021). "Yet, our finding suggests a tumor-suppressive role for AQP3 in deslanoside-treated PCa cells." (PMID 34830961, 2021). "We analyzed the anti-tumor effects of AQP3, CDC20 and COL4A2 targeting alone and in combinations." (PMID 34681181, 2021). "Furthermore, AQP3 inhibition has been shown to prevent apoptotic characteristics in tumor cells by preventing apoptotic-related volume changes." (PMID 33917751, 2021).